BRAF (B-Raf proto-oncogene, serine/threonine kinase)
Diseases named in the same sentence as BRAF in open-access papers (continued):
Sharing a sentence is not in itself a finding about the gene and the disease.
melanoma (continued). "These regulators include MAPK signaling pathway indicators p-BRAF and p-ERK, metastatic markers N-Cadherin and Vimentin, proliferative marker PCNA, and melanoma-specific transcription factor SOX10." (PMID 41284701, 2025). "The final study cohort comprised 490 melanoma patients who either received ICI (Group 1, 384 patients) or BRAF/MEKi (Group 2, 106 patients) as first-line treatment." (PMID 40310541, 2025). "Research on BRAF and MEK inhibitor resistance in melanoma has been conducted across 86 countries and regions." (PMID 39897423, 2025). "Supplemental testosterone mitigates the effects of BRAF + MEK inhibition, and blockade of the androgen receptor (AR) promotes the anti-tumor activity of BRAF + MEK inhibitors in BRAF Class 1 mutant melanoma mouse models." (PMID 38275886, 2024). "We chose a proteomic approach to assess the proportion of MAPK kinase substrates synthesized in an eIF4F-dependent manner in human BRAF- and NRAS-mutant melanoma cells." (PMID 39436655, 2024). "Our studies aimed to understand the molecular mechanisms responsible for resistance to both drugs – BRAF and MEK inhibitors in melanoma models in vitro." (PMID 39175042, 2024). "In mouse melanoma models with BRAFV600E, the MEK inhibitor trametinib demonstrated enhanced antitumor activity when used alongside immunotherapy and the BRAF inhibitor dabrafenib." (PMID 39534873, 2024). "The same study shows that methiothepin also enhances the efficacy of BRAF inhibitor vemurafenib and MEK inhibitor trametinib, used against resistant BRAFV600E melanoma cells." (PMID 38216592, 2024). "Caspase‐3/GSDME pathway is more common in targeted therapy for cachexia, and the combination of BRAF inhibitors and MEK inhibitors (BRAFi + MEKi) has been approved by the FDA for the treatment of melanoma with promising results." (PMID 38652105, 2024). "Providing a foundation, we present a summary of long‐term data derived from clinical trials, aiming to discern the effectiveness of anti‐PD‐1 antibodies or BRAF/MEK inhibitors in preventing recurrence and prolonging survival in melanoma patients." (PMID 38212945, 2024). "Vemurafenib, a BRAF inhibitor drug approved by the FDA, has shown promise in the treatment of BRAFV600E mutant melanoma." (PMID 39063187, 2024). "The current standard-of-care to treat melanoma heavily relies on drugs that inhibit the MEK and BRAF kinases to induce tumor regression by eliciting apoptotic cell death, or at minima to block tumor growth." (PMID 38383439, 2024). "As a corollary, the currently ongoing COLUMBUS-AD will assess a combination of encorafinib (BRAF inhibitor) and binimetinib (MEK inhibitor) in stage IIB/IIC melanoma." (PMID 39123418, 2024). "Upon treatment with BRAF/MEK inhibitors, patients with class 1 mutant melanoma showed numerically longer progression-free survival (PFS; 217 days) than patients with nonclass 1 mutant disease (73 days)." (PMID 41646105, 2024). "Enhanced eIF4F-mediated translation was suggested to partly compensate for lower ERK activity in BRAF and MEK inhibitor-treated melanoma cells." (PMID 39436655, 2024). "Over the last decade, several BRAF and MEK inhibitors have been investigated, ranging from primarily melanoma to various cancer types with BRAF alterations." (PMID 38203795, 2024). "Further studies are required to understand the limits of TGF-β involvement in vemurafenib resistance in melanoma; however, our findings emphasize the role of the TGF-β signalling in BRAF inhibitor resistance and confirm previous findings." (PMID 39063187, 2024). "Interestingly, in patients with stage IV melanoma, lower frequencies of PD-L1+ PMNs in peripheral blood were associated with improved progression-free survival (PFS) and OS compared to those with higher PD-L1+ PMN frequencies only in BRAF wild-type patient subgroup." (PMID 39126091, 2024).
melanoma (continued). "Malignant melanoma patient outcomes have changed drastically with the emergence of immune checkpoint inhibitors (ICI) and BRAF-targeted therapies and the lethality of advanced disease has decreased significantly in the past 10 years." (PMID 39337333, 2024). "The results showed that both BRAF- and NRAS-mutant melanoma cultures were viable after 24 h treatments despite the significant impact of RocA on protein synthesis." (PMID 39436655, 2024). "They transferred EVs from BRAF inhibitor-resistant melanoma to recipient melanoma cells, which resulted in dose-dependent activation of PI3K/Akt signaling and escape from BRAF inhibition." (PMID 38542098, 2024). "The pharmacological inhibition of the mitogen-activated protein kinase (MAPK) signaling pathway by inhibitors of the BRAF and MEK kinases (BRAFi and MEKi) plays an important role in the treatment of patients with advanced malignant melanoma." (PMID 39835134, 2024). "In contrast, the pharmacological induction of TSLP in epidermal keratinocytes promotes the formation and growth of BRAF melanoma, which normally develops slowly and accelerates the progression and metastasis of BRAF/PTEN melanoma." (PMID 39201498, 2024). "The standard treatment of stage III melanoma has changed during this trial, from follow-up after surgery to adjuvant treatment with anti-PD1 antibodies or BRAF/MEK inhibition." (PMID 38395969, 2024). "One tumor with an NRAS G12R mutation had an intrachromosomal chromothripsis event spanning KRAS, while BRAF and NF1 were involved in chromothripsis events in one NRAS melanoma each." (PMID 38758740, 2024). "Class 1 BRAF mutant cancers are targetable with combinations of BRAF, MEK, and EGFR targeted therapies for advanced-stage melanoma, non-small cell lung cancer (NSCLC), and colorectal cancer (CRC)." (PMID 38275886, 2024). "Here, we report and characterize two melanoma cell lines (WM9 and Hs294T) resistant to BRAF (vemurafenib) and MEK (cobimetinib) inhibitors." (PMID 39175042, 2024). "Of note, clinically relevant targets such as BRAF and NRAS have comparable incidences (53–58% for BRAF and 23–28% for NRAS, respectively) thus suggesting the value of larger scale sequencing in the melanoma context." (PMID 38184610, 2024). "The increase in survival rates seen since the advent of BRAF-MEK inhibitors and immunotherapy signifies a major breakthrough in melanoma therapeutics." (PMID 38474231, 2024). "Targeting autophagy together with BRAF and MEK inhibitors has provided clinical benefit for advanced BRAFV600E-mutant melanoma." (PMID 38731852, 2024). "For instance, a high‐fat ketogenic diet has been found to enhance BRAF V600E mutant‐dependent MEK1 activation, leading to increased tumor growth in BRAF V600E‐expressing melanoma cells." (PMID 39494561, 2024). "Immune checkpoint inhibitors (ICIs) and targeted therapy with combined BRAF and MEK inhibitors (BRAF/MEKi) have completely transformed the therapeutic landscape for patients with advanced melanoma." (PMID 38473216, 2024). "This analysis was performed using the responses of three different drugs targeting BRAF: i) Dabrafenib, ii) PLX-4720 and iii) SB590885, and the same set of melanoma-specific features used in the ANOVA analysis." (PMID 39304771, 2024). "To further evaluate the impact of this novel predictive biomarker identified by KL-Relevance approach, we then assessed drug responses in four melanoma cell lines under varying EZH2 and BRAF statuses treated with PLX-4720." (PMID 39304771, 2024). "Randomized clinical trials reporting on CAEs in patients with melanoma being treated with BRAF and MEK inhibitors compared with patients with melanoma being treated with BRAF inhibitor monotherapy were selected." (PMID 39776585, 2024). "We discovered that BRAF inhibitors (BRAFi), commonly used to treat BRAFV600E melanoma, can unexpectedly and effectively promote progenitor cell proliferation by temporarily delaying erythroid differentiation." (PMID 39617757, 2024).
melanoma (continued). "The combined use of BRAF and MEK inhibitors against melanoma has been found to upregulate MHC levels and melanoma differentiation antigens, such as gp-100 and melanoma-associated antigen recognized by T cells (MART-1)." (PMID 38255322, 2024). "BRIM 8 was an international, double-blinded, placebo-controlled phase III trial looking at another adjuvant BRAF V600 inhibitor—vemurafenib—in 498 patients with AJCC Stage IIC, IIIA, IIIB, or IIIC fully resected melanoma." (PMID 39272885, 2024). "The NeoTrio trial investigated combination BRAF-targeted therapy and ICI in the neoadjuvant setting for resectable melanoma, including an anti-PD-1 monotherapy comparator arm." (PMID 38907159, 2024). "In recent years, BRAF- and MEK inhibitors have emerged as a helpful tool in the therapeutic arsenal for melanoma patients." (PMID 39661469, 2024). "A phase 1b clinical trial (NCT03088176) is currently recruiting participants to study T-VEC in combination with BRAF and MEK inhibitors, dabrafenib and trametinib, for the treatment of advanced BRAF-positive melanoma." (PMID 39602056, 2024). "The finding of an increased frequency of MAPK-related mutations and their biological consequences in various cancers, including melanoma, has led to the proposal of various MAPK suppression strategies, such as BRAF and MEK inhibition." (PMID 39519202, 2024). "In a phase 3 clinical trial of adjuvant dabrafenib and trametinib (BRAF and MEK inhibitors, respectively) in patients with resected stage III melanoma, the prognostic value of the five-gene IFN-γ expression signature and the TMB was investigated." (PMID 38540282, 2024). "More commonly, the combination of BRAF inhibitors and MEK inhibitors (BRAFi + MEKi) has been approved by the FDA for the treatment of melanoma achieving favourable results." (PMID 38652105, 2024). "The clinically characterized tumor molecular subtypes included BRAF, NRAS, KRAS, KIT, and PIK3CA mutant melanomas, with BRAF mutant melanomas being more prevalent in AYA compared to adult patients (77% vs 41%; Fisher’s exact test, P = 0.0003)." (PMID 38589406, 2024). "Intriguingly, analysis of a zebrafish model found SOX4 to be a marker of stress-like cell population that more efficiently seeded new tumors; induction of a stress-like program conferred resistance to both BRAF and MEK inhibition in zebrafish melanoma cells." (PMID 39802764, 2024). "Although some other studies on the combination of BRAF or MEK inhibitors and CDK 4/6 inhibitors demonstrated promising antitumor activity in melanoma, this was accompanied by significant toxicity, limiting the applicability of this strategy." (PMID 39684685, 2024). "In contrast to melanomas, colorectal carcinomas express high amounts of EGFR, and this receptor initiates a collateral signaling cascade in response to BRAF inhibition." (PMID 38612902, 2024). "Data indicate that following BRAF inhibition, oxidative phosphorylation (OXPHOS) is activated, leading to high levels of oxidative stress in melanoma cells." (PMID 39501277, 2024). "BRAF and MEK inhibitors, as well as immunotherapy, are promising in treating patients with advanced and unresectable malignant melanoma." (PMID 39175042, 2024). "However, since acral melanoma and mucosal melanoma, which are rare in Western countries but are major subtypes of melanoma in East Asia, including Japan, have a low frequency of BRAF mutations, there are currently no treatment options other than immune checkpoint inhibitors in most such cases." (PMID 38087810, 2024). "Mutant BRAF activates various signaling pathways such as MAPK, ERK, and Akt, which affect the proliferation, migration, and differentiation of melanoma cells." (PMID 39408810, 2024). "In melanoma, tumor suppressive activity of AMBRA1 was correlated with oncogenic BRAF signaling, corroborating previous results." (PMID 39617889, 2024).
melanoma (continued). "BRAF/MEK pathway inhibitors were initially heavily investigated and approved for the treatment of melanomas; however, they have been proven to be effective across various types of cancer with specific alternations over the past decade." (PMID 38203795, 2024). "BRAF and NRAS mutant melanomas histopathologically correlate with low cumulative sun damage (low-CSD) melanomas, while NF1 mutant melanomas are classified as high-CSD." (PMID 38611025, 2024). "Within melanoma, a single study reported on the value of an automated CD8+ TIL density in predicting response to targeted therapy in BRAF mutant tumors." (PMID 38655867, 2024). "Studies have shown that silencing ROCK1 via genetic modulation or inhibition with GSK269962A (a selective ROCK1 inhibitor) enhances the effectiveness of BRAF and MAPK inhibitors against BRAF and NRAS mutant melanoma cells." (PMID 39273383, 2024). "BRAFV600E mutation was detected in PTC and melanoma tissues, and the positivity rate of mutant BRAF was higher in presurgical ctDNA than in samples collected after the treatment for PTC and melanoma (99.8% vs. 0.07%)." (PMID 39336882, 2024). "We found that inhibiting BRAF, a constitutive part of the MAPK pathway, profoundly changes tumor metabolism in melanoma phenotypes with high BRAF dependence." (PMID 38254853, 2024). "BRAF/+/melanoma patients exhibited higher 2‐year RFS rates in the entire cohort and the BRAF/MEK inhibitor‐treated group compared to those treated with anti‐PD‐1 antibodies." (PMID 38212945, 2024). "These BRAFV600-mutant monomers are targeted by class I or monomer-selective BRAF inhibitors (BRAFi), approved for use in combination with MEK inhibitors (MEKi) in BRAFV600-mutant melanoma." (PMID 39682270, 2024). "The introduction of BRAF and MEK inhibitors has revolutionized the treatment landscape for melanoma patients." (PMID 39582535, 2024). "Therefore, inhibitors of PAX3/MITF expression may sensitize melanomas to BRAF/MEK inhibitors." (PMID 38473380, 2024). "Whilst inhibitors of KRASG12C (lung adenocarcinoma) and BRAF and MEK1/2 (melanoma and colorectal cancer) are clinically approved, acquired resistance remains a problem." (PMID 38381045, 2024). "Within each tumor type, the risk of brain metastasis is related to disease status and molecular subtype (i.e., EGFR-mutant non-small cell lung cancer, HER2-positive and triple-negative breast cancer, BRAF and NRAF-mutant melanoma)." (PMID 38893253, 2024). "Together, these results support a combination therapeutic strategy using BRAF inhibitors to target the tumor bulk and NAZ to eradicate the ALDH1A3-melanoma stem cell pool in the residual disease." (PMID 38963759, 2024). "Targeted therapies aimed at mutant BRAF and downstream MAPK signaling components are effective treatments against BRAF-V600E/K-positive melanoma." (PMID 38839106, 2024). "Examples of this strategy are the combination of BRAF and MEK inhibitors to delay resistance in malignant melanoma." (PMID 39184861, 2024). "Targeting metabolic pathways in melanoma is crucial for overcoming therapeutic resistance, particularly in MAPK pathway inhibitor (MAPKi)‐resistant BRAF‐mutant tumors." (PMID 39494561, 2024). "Similar to melanoma, superior efficacy of combined BRAF and MEK inhibition compared to BRAF inhibitor monotherapy was observed in BRAFV600E-mutant NSCLC." (PMID 38177660, 2024). "BRAF inhibitors, such as PLX4032, which have been reported to upregulate PGC1α expression in melanomas, inhibit metastasis partly by suppressing the Wnt/β-Catenin-MITF pathway and promoting the expression of PGC1α." (PMID 38774408, 2024). "The DREAMseq trial confirmed that preferred nivolumab/ipilimumab followed by BRAF and MEK inhibitor therapy has better control of melanoma, providing a practical clinical treatment reference." (PMID 38835341, 2024).
melanoma (continued). "In one study, primary melanoma cells (M160915) and established cell lines (A375, WM983A, UACC903) with resistance to the BRAF inhibitor dabrafenib were analyzed and it was found that the AR and its downstream pathway were upregulated." (PMID 38255778, 2024). "Melanoma treatment has greatly expanded in recent years due to the introduction of ICI and BRAF/MAPK-targeted therapies." (PMID 39337333, 2024). "One example is melanoma, in which combination therapy with BRAF and MEK inhibitors provides 34% overall 5-year survival in BRAF-activated metastatic melanoma." (PMID 39212544, 2024). "The favorable impact of neutrophils on melanoma cells was not confined to targeted therapy; it was also evident in cisplatin-treated conditions, thereby expanding the neutrophil-induced protection to other treatment regimens, which can be applied independent of the prevalence of BRAF mutations." (PMID 38730718, 2024). "Autophagy, a catabolic cellular process that replenishes nutrients and restores damaged organelles, has been identified as s resistance mechanism to combined BRAF and MEK inhibition in melanoma." (PMID 38731852, 2024). "All NRAS-mutant melanomas demonstrated IC50 values in the micromolar range, with a 3-fold average lower sensitivity to corin versus BRAF-mutant melanomas." (PMID 38300709, 2024). "Our results are in agreement with previous studies showing that the activation of BRAF promotes senescence and/or apoptosis, whereas the silencing of CRAF in melanoma cells induced apoptosis." (PMID 38540084, 2024). "Combined BRAF and MEK inhibition or transfection of 3pRNA alone only slightly increased the frequency of dead A375 cells but killed almost half of Ma-Mel-48 melanoma cells." (PMID 39165562, 2024). "BRAF-mutant melanomas exhibit fewer CD8+ T cells and more B cells and CD4+ T cells than BRAF wild-type tumors." (PMID 39582535, 2024). "Therapeutic advances in melanoma have resulted in the FDA approval of immune checkpoint inhibitors and several generations of BRAF-targeted therapies for patients with BRAF V600E mutant tumors." (PMID 38611025, 2024). "Potential treatment alternatives include BRAF/MEK inhibitors, which have been useful in the treatment of various cancers like CDKN2A-negative melanoma, and CDK4/6 inhibitors, which have been approved to treat breast cancer." (PMID 38612819, 2024). "A phase I trial found durvalumab in combination with dabrafenib (a BRAF inhibitor) and trametinib (a MEK inhibitor) to be feasible for the treatment of BRAF-mutant melanoma." (PMID 39081713, 2024). "Upregulation of NOX5 expression enhances cell proliferation and resistance to BRAF inhibition therapy, while NOX1 overexpression favors melanoma invasion." (PMID 39519202, 2024). "However, BRAF mutations do not predominate in canine melanomas." (PMID 39272320, 2024). "As for NES, we found higher expression in BRAF+ melanoma than in BRAF− melanoma and significantly higher expression than in dysplastic nevus and melanoma in situ, emphasizing the significance of NES in melanoma progression." (PMID 39273022, 2024). "Cutaneous adverse events (CAEs) after treatment with BRAF and MEK inhibitors in patients with melanoma remain incompletely characterized." (PMID 39776585, 2024). "A375 melanoma cells show isoform dependency on MAPK1/MAP2K1, also observed in DepMap screens in BRAF-driven melanoma cells." (PMID 38678031, 2024). "The presence of BRAF mutation in colorectal cancer is by itself a negative prognostic factor, as therapeutic strategies utilizing medications aimed at BRAF-V600E in CRC have shown comparatively lesser efficacy than, for example, in BRAF mutant melanoma." (PMID 38539463, 2024). "By inducing BRAF 600E expression and silencing PTEN, they generated primary melanomas with high penetrance, short latency, and lymph node metastasis." (PMID 38775220, 2024).